CD36 (CD36 molecule (CD36 blood group))
Diseases named in the same sentence as CD36 in open-access papers (continued):
Sharing a sentence is not in itself a finding about the gene and the disease.
pulmonary edema (1 paper, 2013). Accumulation of fluid in the lung tissues causing disturbance of the gas exchange that may lead to respiratory failure. "The results reported here support a mechanism in which iRBC interactions with CD36 initiates Fyn-mediated signaling that leads to an alteration in endothelial cell barrier function and pulmonary edema." (PMID 23967147, 2013). "A prominent feature of the lung pathology in humans and mice is pulmonary edema, suggesting that CD36-iRBC interactions could contribute directly or indirectly to alterations in endothelial cell barrier integrity." (PMID 23967147, 2013).
purpura (1 paper, 2026). A small blood vessel hemorrhage into the skin and/or mucous membranes. "In the possible PTP case, massive transfusion was started on Day 8 of hospitalization, purpura appeared on Day 15, anti-CD36 was identified on Day 21, and CD36-negative platelet transfusion was initiated on the following day." (PMID 41702681, 2026).
Rb (1 paper, 2022). "Immune-related genes such as CD86, CD19, and CD36 were significantly upregulated in advanced Rb while displaying a low degree of expression of CD81 and CD163." (PMID 35626705, 2022).
respiratory infection (1 paper, 2022). "It was also reported that adult C57Bl/6J mice with the CD36-/- phenotype (scavenger receptor expressed predominantly in macrophages) have a higher pulmonary bacterial load and greater extrapulmonary dissemination after respiratory infection induced with hypermucoviscous K. pneumoniae." (PMID 35806365, 2022).
sarcoidosis (1 paper, 2021). Sarcoidosis is a multisystemic disorder of unknown cause characterized by the formation of immune granulomas in involved organs. "Likewise, expression of the CD36 scavenger surface marker was maintained under hypoxic condition in MD-macrophages from sarcoidosis in contrast to controls." (PMID 34456926, 2021).
scrapie (1 paper, 2022). A fatal disease of the nervous system in sheep and goats, characterized by pruritus, debility, and locomotor incoordination. "In this region, the expression of TLR2, 3, 4, 6, 7, 8, 9, and CD36 was significantly higher (p < 0.01) in the scrapie-infected versus control animals." (PMID 35408945, 2022). "In the thalamus, TLR6, MyD88, and CD36 were significantly upregulated in the scrapie-infected group (p < 0.05), while TLR2 and TLR3 displayed a tendency towards upregulation (p < 0.1)." (PMID 35408945, 2022).
skin cancer (1 paper, 2017). "High levels of VEGFR 2 expression may contribute to a change in TSP-1 initiated CD36 signaling in different types of cancer including breast, brain, colon, lung, and skin cancer." (PMID 28186980, 2017).
staphylococcal pneumonia (1 paper, 2012). Pneumonia caused by infections with bacteria of the genus staphylococcus, usually with staphylococcus aureus. "Mice with deletions of MSR1 or CD36 have increased susceptibility to pneumococcal or staphylococcal pneumonia." (PMID 22396727, 2012).
tendinitis (1 paper, 2024). Inflammation of a tendon, usually resulting from an overuse injury. "The qPCR results showed that CD36 and MYD88 were significantly elevated in patients with tendinitis compared to healthy controls." (PMID 38919626, 2024). "Additionally, our study highlights key molecular pathways, immune cells, and transcription factors involved in tendinitis, such as the roles of MYD88, CD36, CREB5, and ELF4." (PMID 38919626, 2024).
thrombotic disease (1 paper, 2016). The formation of a blood clot in the lumen of a vessel or heart chamber; causes include coagulation disorders and vascular endothelial injury. "Given that AOPPs are recognized by several scavenger receptors involved in cardiovascular disease, including CD36, the receptor for advanced glycation end-products and SR-BI9, 10, 33, 46, AOPPs might play a considerable role in the onset and progression of cardio-thrombotic diseases." (PMID 26905525, 2016).
thyroid disorders (1 paper, 2021). "In a recent study, an HFD fed mouse with thyroid disorders for 16 weeks reported a significant reduction in Glut2, Pept1, and fatty acid translocase (FAT/CD36) expressions, indicating that HFD may impair nutrient intake in the small intestines." (PMID 34646544, 2021).
uremia (1 paper, 2021). A clinical syndrome associated with the retention of renal waste products or uremic toxins in the blood. "THP-1 cells treated with PMA and then exposed to uremia, showed increased ABCA1, CD36, and PLIN2 expression compared to macrophages exposed to normal serum." (PMID 33536542, 2021).
uveitis (1 paper, 2023). An inflammatory process affecting a part of or the entire uvea. "(G) Manual gating strategy of CD1c+ DC subsets based on CD36 and CX3CR1 in PBMCs in uveitis cases and controls." (PMID 37042831, 2023). "Comparison between patients and controls corroborated that the frequency of manual gated CD36+CX3CR1+ DC3s were decreased in the blood of non-infectious uveitis patients (Welch t-test, p = 0.029)." (PMID 37042831, 2023). "Single-cell analysis supported that CD1c+ DCs in eye fluid of patients with non-infectious uveitis contain also a population that has a gene profile reminiscent of CX3CR1+ DC3s, with relatively higher levels of CX3CR1, CD36, CCR2, and lower levels of RUNX3." (PMID 37042831, 2023).
vascular tumors (1 paper, 2012). "TSR expressing B16F1 cells produced larger and more vascular tumors in cd36 null mice (7A left and 7B top) and smaller and less vascular tumors in hrgp null mice (7A right and 7B bottom) when compared to age and sex matched wildtype controls." (PMID 22808089, 2012).
vitiligo (1 paper, 2022). Generalized well circumscribed patches of leukoderma that are generally distributed over symmetric body locations and is due to autoimmune destruction of melanocytes. "In contrast with this, the CD36 gene and protein expressions were upregulated by PGZ in vitiligo fibroblasts and melanocytes." (PMID 36429011, 2022). "Therefore, we evaluated whether CD36 could be modified by PGZ in vitiligo cells." (PMID 36429011, 2022).
tumor (678 papers, 1990 to 2026). "By using fatty acid oxidation, CD36 lead to the production of reactive oxygen species and to transcription of genes mediating a pro-tumor function, inducing tumor-associated macrophages (TAM)." (PMID 42164471, 2026). "The EFFscore comprises three genes—ADAM9, P2RY6 and CD36—all of which have been closely associated with tumor progression." (PMID 41383622, 2025). "Cluster 1 contained genes significantly upregulated in AMPKα1/α2–deficient tumor-infiltrating Treg cells and included genes encoding chemokines (Ccl2, Ccl7, Ccl8), modulators of lipid metabolism (Cd36, Pparg, Lpl, Abca1), and glycolytic enzymes (Hk2, Hk3)." (PMID 40100289, 2025). "Elevated CD36 expression in tumor-infiltrating CD8 + T cells is associated with tumor progression and poor survival in both human and murine cancers." (PMID 41326356, 2025). "Tumor-associated macrophages (TAM) are specifically affected by CD36-mediated lipid over-uptake, which results in oxidative phosphorylation failure, lipid droplet accumulation, and M2 phenotypic polarization." (PMID 41451233, 2025). "Targeting of CD36 and its associated mechanisms is currently being explored to mitigate tumour cells lipid uptake from CAAs." (PMID 39965288, 2025). "Specifically, increased expression of CD36 on CD8+ TILs has been linked to tumor progression and poor survival rates in cancer patients." (PMID 41009695, 2025). "On the other hand, CD36 protein expression in GC tissue has been linked to tumour progression and metastasis." (PMID 41154605, 2025). "On a different note, certain surface markers expressed by tumor cells, such as CD36, have been associated with metastasis, monocyte infiltration, and the subsequent differentiation of these monocytes into pro-tumor M2 macrophages." (PMID 40725201, 2025). "It is also noteworthy that CD36 expression is often diminished in tumor-associated stroma, contributing to metabolic rewiring and tumor progression." (PMID 40565366, 2025). "CD36 displayed both tumor-promoting and immune-inflamed associations, with dual links to prognosis and immunotherapy outcomes that emphasize its context-dependent functions in the tumor microenvironment." (PMID 41550652, 2025). "In tumor-associated macrophages, upregulated CD36 increases lipid uptake, enhancing fatty acid oxidation and mitochondrial ROS production, which activates JAK1 phosphorylation, SHP1 dephosphorylation, and STAT signaling, promoting pro-tumor TAM polarization." (PMID 41474538, 2025). "Excessive lipid accumulation caused by elevated CD36 levels in CD38+ T-cells impairs secretion of anti-tumor factors (IFN-γ, TNF-α)." (PMID 40563926, 2025). "Recent studies have highlighted the role of CD36 in mediating lipid uptake by tumor-associated immune cells and promoting tumor cell progression." (PMID 40940956, 2025). "Tumor-associated macrophages (TAMs) accumulate lipids by enhanced lipid uptake mediated through upregulation of CD36." (PMID 41009695, 2025). "CD36 upregulation on natural killer (NK) cells also impairs tumor-killing caused by intracellular lipid accumulation and cell dysfunction." (PMID 40563926, 2025). "A recent report by Yang et al91 found that metastasis-associated macrophages in the liver rely on CD36 to engulf tumor cell–derived LCFAs, which drives the metabolic and functional reprogramming of macrophages and promotes liver metastasis of multiple cancers." (PMID 39774047, 2025). "The up‐regulated genes in tumor‐infiltrating myeloid cells in RARα‐KO mice included Rnf128, Cd36, Nos2, Prdx1, Cd274, and H2‐Q4, associated with the immune‐activating phenotype." (PMID 40068101, 2025). "High infiltration of CD36 + M2 tumour-associated macrophages (TAMs) and elevated CD47 expression in NEPC cells are often associated with poor progression-free survival in cancer patients." (PMID 41163221, 2025). "Previous studies have indicated that reduced stromal CD36 is associated with increased tumor aggressiveness." (PMID 40565366, 2025).
tumor (continued). "High CD36 expression was significantly associated with the primary site (p = 0.0011), tumor stage (p = 0.026), differentiation (p = 0.013), mode of invasion (p = 0.0034), and recurrence (p = 0.0004)." (PMID 41465497, 2025). "It is reported that CD36 is upregulated in cancer-associated fibroblasts (CAFs) in comparison to peri-tumor fibroblasts (PTFs) in HCC, resulting in the altered lipid metabolism in tumor cells." (PMID 38833109, 2024). "CD36 is highly expressed on macrophages, and its expression is increased in tumor-associated metastasis-associated macrophages and BMDMs." (PMID 39317708, 2024). "In hepatocellular carcinoma, CD36 expression in tumor cells was positively associated with increased glycolysis and lactic acid production." (PMID 39742252, 2024). "Genetic deficiency of Cd36 diminishes the uptake of fatty acids by Treg cells, resulting in intratumoral Treg cell apoptosis and impeding tumor growth." (PMID 38565887, 2024). "This review covers recent data on phenotypic characterization of homeostatic, atherosclerotic, lipid-, tumor- and metastatic-associated macrophages, with the integral role of CD36 highlighted." (PMID 39742252, 2024). "Genetic deletion of Cd36 (encoding the oxLDL transportation protein CD36) increases the percentage of these “stem-like T cells” among tumor antigen-specific CD8 + T cells." (PMID 38565887, 2024). "Tumor-infiltrating CD8 + T lymphocytes absorb FA via CD36, which also causes ferroptosis and lipid peroxidation in the TME." (PMID 38302980, 2024). "Expression of full-length TSP-1 causes tumor reduction by CD36-dependent induction of apoptosis in tumor cells and endothelial cells." (PMID 38218979, 2024). "CD36-mediated lipid uptake enhances fatty acid oxidation (FAO) in tumor-associated macrophages (TAM) as well as in myeloid-derived suppressor cells (MDSCs) to promote a protumor microenvironment." (PMID 39062552, 2024). "CD36-mediated fatty acid uptake in tumor-infiltrating CD8+ T cells activates lipid peroxidation and iron apoptosis, while CD36 deficiency inhibits tumor growth." (PMID 39763649, 2024). "CD36 plays an important role in the tumour microenvironment as well, where it enhances the function of tumour-associated macrophages and aids in tumour proliferation." (PMID 38610991, 2024). "Upregulation of CD36 in metastasis-associated macrophages (MAMs) promotes tumour cell-derived fatty acid uptake, protumoural polarization and their supportive role in the establishment of liver metastasis." (PMID 38969865, 2024). "Recently, further studies have linked CD36 to tumor progression and treatment resistance via increased lipid uptake and FA oxidation (FAO) for ATP production 1,17-20." (PMID 38370376, 2024). "Specifically, CD36 expression on CD8+ TILs has been linked to tumor progression and poor survival rates in cancer patients." (PMID 37700339, 2023). "CD36 has also been associated with TME-induced tumor growth and metastasis and inhibition of the immune response." (PMID 37153595, 2023). "Increased CD36 expression in tumor-infiltrating CD8+ T cells was associated with tumor progression and poor survival in human and murine cancer models." (PMID 37639069, 2023). "It was shown that CD36 levels decreased over the course of the cellular differentiation of CSCs [4716 Conversely, the downregulation of CD36 via an siRNA treatment was shown to result in loss of self-renewal and tumor initiating ability." (PMID 37371076, 2023). "CD36 plays a role in the polarization and function of tumor-associated macrophages (TAMs), which has been associated with a pro-inflammatory phenotype and increased tumor-promoting activities." (PMID 37999824, 2023). "Increased expression of CD36 was significantly associated with higher tumor status, tumor grading, and lymph node metastasis rate, exhibiting an over 40-fold increase in oral cancers." (PMID 37927468, 2023).
tumor (continued). "Et.al observed that metastasis-associated macrophages (MAM) upregulate CD36, which fuel macrophage-tumor crosstalk and reshape the TME." (PMID 37207149, 2023). "Stromal CD36 loss during tumor progression reflects impairment of PPARγ expression by tumor-derived factors." (PMID 37816052, 2023). "Increased expression of the CD36 fatty acid transporter in tumor-infiltrating CD8+ T cells has been associated with poor clinical outcomes in patients receiving PD-1 inhibitor therapy." (PMID 37612411, 2023). "A previous report indicates that CD36 expression distinguishes healthy from tumor-associated breast stroma." (PMID 37816052, 2023). "Multivariable analysis showed that besides tumor size and tumor invasion, the ratio of CD36+CD8+T cells was also an independent risk factor for OS (p = 0.005) and RFS (p < 0.000)." (PMID 37085798, 2023). "These conclusions reveal ferroptosis of CD8+ T cells as a new pattern of tumor immunosuppression and highlight the underlying treatment of blocking CD36 to enhance antitumor immunity." (PMID 36845720, 2023). "In glioblastoma, for example, CD36 was found to be a key marker of stemness and was implicated in facilitating tumor initiation and growth." (PMID 37371076, 2023). "As an example, it has been indicated that lipid oxidative phosphorylation and elevated lipid uptake are necessary for the polarization of tumor-associated macrophages, and CD36, the lipid uptake-associated molecule is determined to be a promising tumor marker." (PMID 37346073, 2023). "CD36 silencing in Tregs inhibited tumor growth, decreased tumor-associated Tregs and enhanced the anti-tumor activity of tumor-infiltrating lymphocytes without significantly impacting immune homeostasis." (PMID 36038892, 2022). "CD36 mediates the uptake of FAs by CD8+ tumor-infiltrating T cells and is also implicated in lipid peroxidation and ferroptosis." (PMID 36131916, 2022). "Recently, Yang and collaborators described the metabolic crosstalk between tumor cells and macrophages in liver metastases, in which CD36 is upregulated in the metastasis-associated macrophages that participate in creating an immunosuppressive TME." (PMID 36568966, 2022). "Recently, Ma and colleagues discovered that higher expression of CD36 is associated with shorter survival since CD36-mediated ferroptosis of tumor-infiltrating CD8+ T cells restricted antitumor immunity." (PMID 35627105, 2022). "Studies investigating tumor-associated macrophages (TAMs) show that blocking CD36-mediated uptake of oxidized lipids by TAMs significantly reduces tumor progression by reducing pro-tumor cytokines produced from TAMs." (PMID 35991116, 2022). "It was reported that tumor-infiltrating CD8+ T cells with CD36 deficiency had low expression of FRGs, and CD36 deficiency had been confirmed to be associated with reduced ferroptosis in tumor-infiltrating CD8+ T cells." (PMID 34979993, 2022). "Another study demonstrated that in several cancer types including CRC, tumor associated macrophages (TAMs) expressed elevated levels of the scavenger receptor CD36, accumulated lipids and utilized FAs for energy production." (PMID 35323656, 2022). "CD36 mediates the internalization of tumor-associated lipids, which subsequently drives the metabolic and functional reprogramming of macrophages." (PMID 36184646, 2022). "Recent studies have found that CD36-mediated lipid metabolism on tumor-associated immune cells promotes tumor progression." (PMID 36354702, 2022). "CD36, an FA translocase, is a crucial molecule in FA transport from adipocytes to cancer cells, and overexpression of CD36 is associated with tumor progression and metastasis; crucially, CD36 is up-regulated by RAGE-mediated signaling." (PMID 35727208, 2022). "As expected, the expression of CD36 was increased in tumor-associated MAMs and BMDMs as compared with native macrophages." (PMID 36184646, 2022).